KRT17 (keratin 17)
Diseases named in the same sentence as KRT17 in open-access papers (continued):
Sharing a sentence is not in itself a finding about the gene and the disease.
cervical carcinoma (continued). "In cervical carcinoma, keratin 17 was always detected, so the development of carcinoma from CIN-III is restricted to CK17 positive CIN-III." (PMID 28855930, 2016). "In the present study, we focused on KRT13 as a candidate radioresistance gene because certain keratins (KRTs) are reportedly shown to have cancer stem-like properties, including KRT19 in hepatocellular carcinoma and colorectal cancer, KRT6 in lung cancer and KRT17 in cervical cancer." (PMID 36610719, 2023). "KRT17 has been identified as an oncogene in cervical cancer." (PMID 36610719, 2023). "Considering that KRT17 may be a gene related to the radiotherapy sensitivity of cervical cancer, we assessed KRT17 and found that it was abnormally expressed in a variety of tumors after reviewing the literature." (PMID 35646078, 2022). "Moreover, KRT17 knockout has been found to inhibit cell viability and migration of cervical cancer cells and increase paclitaxel sensitivity to chemotherapy." (PMID 35281081, 2022). "In cervical cancer, high KRT17 expression is correlated with advanced tumor stages and poor patient prognosis, and KRT17 loss induces tissue-specific cytokine polarization and effector immune cell recruitment to foster the creation of a protective environment for lesion-prone cervical tissue." (PMID 29100303, 2017). "Indeed, keratin expression has been correlated with cervical cancer progression, with keratin 17 prominently expressed at various tissue depths of dysplastic tissue." (PMID 21931846, 2011). "In addition, studies have shown that KRT17 also effects the proliferation, apoptosis and migration of cervical cancer cells through a regulatory axis involving lncRNA miR205HG -SRSF1-KRT17 and TGF- B1-ERK1/2-MZF1 -KRT17, thus enhancing the characteristics of cervical cancer stem cells." (PMID 35281081, 2022). "Furthermore, MIR205HG could also target SRSF1 and modulate KRT17 to mediate biological activities of cervical cancer cells." (PMID 34926294, 2021). "During the progression of cervical cancer, from normal cervical tissues to CIN 1, 2 and 3, the up‐regulated genes we confirmed were SYCP2, NEFH, CDKN2A and KRT17." (PMID 33624385, 2021). "KRT17 (CK17), TP63 and CDK2A (P16), markers of HPV target cells/cervical cancer stem cells (CSCs), were apparently upregulated in CIN and SCC." (PMID 34257574, 2021). "In summary, using a gene‐level to protein‐level analysis, our results demonstrate that KRT17 and CRISP2 are specifically expressed in various histological stages of cervical carcinoma." (PMID 33624385, 2021). "A previous study reported that MIR205HG inhibits progression of cervical cancer by interacting with SRSF1 and modulating KRT17 expression." (PMID 33535182, 2021). "The presence of cervical cancer stem cells (CCSC) has been determined through the expression of CD49f and cytokeratin 17 (CK17)." (PMID 30257666, 2018). "Therefore, we proposed that combined analysis of KRT17 and CRISP2 expression to determine different histological stages of cervical cancer, it would be helpful for accurate histological diagnosis." (PMID 33624385, 2021). "In cervical cancer for instance, KRT17 was induced by TGF-β1 to activate ERK1/2-MZF1 signaling pathway and enhance acquisition of CSC properties, while another study showed that KRT17 expression was greatly increased in cultured cervospheres and was correlated with tumorigenicity." (PMID 35706019, 2022). "Therefore, KRT17 may be a good biomarker for cervical cancer and a lack of KRT17 expression strongly suggests a normal cervix." (PMID 33624385, 2021). "There was a positive correlation between KRT17 expression and macrophage infiltration in LIHC, THCA, THYM, and UVM, but no positive correlation was found in cervical cancer." (PMID 35646078, 2022). "Immunohistochemical (IHC) results confirmed that keratin 17 (KRT17) was not expressed in normal cervical tissues and was over‐expressed in cervical cancer." (PMID 33624385, 2021).
pancreatic cancer (26 papers, 2010 to 2025). "In addition, the high expression of KRT17 is associated with basal-like molecular sub-types of pancreatic cancer, while the low expression of KRT17 is typically associated with pancreatic cancer." (PMID 35281081, 2022). "TCGA database indicated that the level of KRT17 in pancreatic cancer was increased than in normal pancreatic tissues (P < 0.05)." (PMID 38434984, 2024). "As per the findings of this research, upregulation of miR-485-5p restrain KRT17 overexpression in pancreatic cancer cells line, inhibiting the biological functions of cell invasion, proliferation, and cloning and promoting cell apoptosis." (PMID 38434984, 2024). "In this study, KRT17 expression in pancreatic cancer cell lines (PANC-1 and SW1990) was up-regulated about normal pancreatic cells (H6c7)." (PMID 38434984, 2024). "Many studies have suggested that KRT17 exerts a pro-carcinogenic effect in other types of cancer (e.g., lung cancer, Ewing’s sarcoma, pancreatic cancer, esophageal cancer and oral squamous carcinoma)." (PMID 36765563, 2023). "In pancreatic cancer overexpression of KRT17 was shown to decrease CyclinD1 levels and increase cleaved caspase 3 amounts causing cell cycle arrest and apoptosis." (PMID 37024667, 2023). "ANXA1 and KRT17 consistently demonstrated expression trends that concurred with our overall bioinformatics analysis in six out of seven pancreatic cancer patients, indicating heightened expression in tumor tissues." (PMID 37941546, 2023). "We also noticed that some organoids gained expression of the pancreatic cancer basal cell marker KRT17." (PMID 36352230, 2022). "Various studies have shown that KRT17 is overexpressed in many cancers, including cervical, oral, ovarian, gastric, lung and pancreatic cancer." (PMID 36139022, 2022). "Both KRT17 protein and mRNA were highly expressed in pancreatic cancer tissues, while they were expressed at low levels in normal pancreatic tissues." (PMID 35281081, 2022). "Most commonly, KRT17 is overexpressed in cancers (including cervical, oral, ovarian, gastric, lung and pancreatic cancers), and this increased expression is related to adverse outcomes." (PMID 36139022, 2022). "In recent years, studies have shown that KRT17 is abnormally expressed in a variety of malignant tumours, and up-regulated in lung cancer, pancreatic cancer, gastric cancer and sarcoma." (PMID 35281081, 2022). "Increased level of KRT17 is directly correlated with the progression of pancreatic cancer." (PMID 36949761, 2023). "Moreover, KRT17 advances carcinogenesis of skin cancer, non-small-cell lung cancer, renal cell carcinoma, pancreatic cancer, and hepatocellular carcinoma." (PMID 36248412, 2022). "However, KRT17 knockdown has been reported to promote pancreatic cancer cell migration and invasion." (PMID 36139022, 2022). "Similarly, KRT17 mRNA and protein levels were highly expressed in pancreatic cancer cell lines." (PMID 35281081, 2022). "In pancreatic cancer tissues, ADM, KRT17, and ANXA1 protein levels surpassed those in normal samples, while C7 and ALB protein levels exhibited a declining trend, in accordance with the findings from qRT-PCR and bioinformatics analysis." (PMID 37941546, 2023). "The best three single-gene discriminators are KRT17, COL10A1 and CTHRC1 for pancreatic cancer, having the same classification accuracy, 93.6% on the training set and 88.5% and 80.4%, 84.6% and 73.2%, and 84.6% and 85.7% on the two test sets, respectively." (PMID 21060876, 2010). "However, in several studies, it has been suggested that KRT17 and ANXA10 are related to pancreatic cancer." (PMID 30953499, 2019). "KRT17 might contribute to the induction of oxLDL-absorbing neutrophils, and it is preferentially expressed in advanced GBC and correlates with poorer survival in bile duct cancer and pancreatic cancer." (PMID 38822440, 2024).
skin tumor (24 papers, 2013 to 2025). "Keratin-17 has been implicated in skin cancer progression by modulating the TH1–TH2 T-cell phenotype balance and also has been shown to play a role in cervical squamous cell tumor biology by binding to and exporting the tumor suppressor p27KIP1 from the nucleus." (PMID 29443941, 2018). "Immunofluorescence staining of tail epidermis whole mounts revealed that the BCC-like lesions in the three mouse models were positive for the basal keratinocyte marker keratin 5 (K5) and the basaloid skin tumor marker keratin 17 14 (K17)." (PMID 40060632, 2025). "For instance, the expression levels were up-regulated of KRT17 encouraging cell proliferation and tumorigenesis in skin tumors, oral and cervical squamous cell carcinoma, gastric and lung cancer, and other tumors 31-35." (PMID 38434984, 2024). "A previous study in skin cancer cells showed that a cytoskeletal protein keratin 17 (K17) is required for the cytoplasmic localization of HNRNPK, demonstrating that keratin is a regulator of HNRNPK localization." (PMID 37592256, 2023). "It is shown that KRT17 promotes the proliferation and invasion of skin tumors through the KRT17/HNRNP-K/CXCR3 pathway." (PMID 36553210, 2022). "The high expression levels of Rac1 increase the levels and interactions of CD11b + Gr1 + cells, induce KRT17 to regulate inflammation and promote the formation of skin tumors." (PMID 35281081, 2022). "KRT17 also promotes the proliferation and invasion of skin tumours through the KRT17/HNRNP-K/CXCR3 pathway." (PMID 35281081, 2022). "In conclusion, Rac1 appeared to promote skin tumor formation by activation of an IFN-keratin 17 loop and through recruitment of CD11b+Gr1+ cells." (PMID 24962779, 2014). "Our results suggested that hyperactive Rac1 recruited and interacted with CD11b+Gr1+ cells, inducing keratin 17-regulated inflammation and promoting skin tumor formation." (PMID 24962779, 2014). "In addition, KRT17 can also promote the release of inflammatory cytokines, and promote the occurrence and development of skin tumours by inducing inflammation." (PMID 35281081, 2022). "Therefore, keratin 17 is a marker of skin tumour cell proliferation." (PMID 35281081, 2022). "Studies have shown that Autoimmune regulator (Aire), a transcriptional regulator, induces KRT17 dependent expression in human and mouse tumour keratinocytes and requires GLI-2 induced skin tumour development in mice." (PMID 35281081, 2022). "KRT17 together with KRT16 and KRT6 are involved in keratinocyte differentiation and skin cancer." (PMID 28852586, 2017). "Among the upregulated genes in SCC were several genes known to be involved in keratinocyte differentiation and skin cancer, including keratins (e.g. KRT16, KRT17 and KRT6), matrix metalloproteinases (MMPs), S100 molecules and small proline-rich proteins (SPRRs)." (PMID 23379751, 2013).
squamous cell carcinoma (21 papers, 2010 to 2024). A carcinoma arising from squamous epithelial cells. "Cytokeratin 17 (CK17) is an epithelial marker for squamous cell carcinoma, and its expression is associated with the differentiation and malignancy of OSCC." (PMID 35444950, 2022). "We utilized the A431 keratinocyte cell line, an established model derived from human epidermoid carcinoma, which expresses K17 at baseline in culture and for which we have a KRT17 null variant." (PMID 39159283, 2024). "Stress keratin 17 is overexpressed in several types of human squamous cell carcinomas (SCC), and its overexpression is correlated with poor prognosis in SCC patients." (PMID 31968015, 2020). "Expression of KRT17 has been described in bladder carcinoma, keratoacanthoma and squamous cell carcinoma, oral squamous cell carcinoma, premalignant and malignant squamous lesions of the cervix, all derived from multilayer epithelial cells 7-10." (PMID 31602265, 2019). "In addition, KRT17 can regulate proliferation of cancer cell, and induce the proliferation of squamous cell carcinoma cells." (PMID 33441834, 2021). "Finally, human squamous cell carcinomas are characterized by the expression of KRT14 and KRT17." (PMID 33142242, 2020).
oral squamous cell carcinoma (20 papers, 2011 to 2025). "Besides, cytokeratin 17 (CK17) is thought to be a diagnostic marker of oral squamous cell carcinoma (OSCC)." (PMID 31857991, 2019). "For example, an increased expression level of KRT17 was shown for 101 out of 105 (96.2%) oral squamous cell carcinoma specimens examined, and the expression level was higher in well-differentiated oral SCC compared to moderately/poorly differentiated oral SCC." (PMID 38540309, 2024). "Here, we demonstrate that KRT17 is invariably and permanently induced in oral squamous cell carcinoma (OSCC), as revealed by immunohistochemistry and cDNA microarray analysis." (PMID 27512993, 2016). "Abnormal expression of keratins is reported in cancer cells and the keratin profiling of oral squamous cell carcinoma exhibited higher expression of keratins such as KRT6, KRT16, and KRT17." (PMID 36393868, 2022). "We previously engaged in comprehensive keratin profiling in oral squamous cell carcinoma (OSCC) and found that KRT6, KRT16, and KRT17 were upregulated." (PMID 27512993, 2016). "KRT17 is known to be a direct target of miR-485, while the signaling cascade involving miR-485/KRT17 may result in suppressing EGFR in oral squamous cell carcinoma cell lines." (PMID 36902387, 2023). "KRT17 expression level is confirmed to be elevate in most OSCC cell lines (BHY, BICR 1, BICR 7, HN, as evidenced in RNAseq (ArrayExpress ID: “E-MTAB-2706”) and array public experiments (E-GEOD-30784, log2FC=4.1 for “oral squamous cell carcinoma vs normal samples”, p-value=2.19E−38)." (PMID 29285222, 2017).
gastric cancer (19 papers, 2016 to 2025). A primary or metastatic malignant neoplasm involving the stomach. "For instance, miR-485-5p has been shown to downregulate KRT17, a keratin associated with aggressive tumor behavior, thereby suppressing tumor growth in gastric cancer, both in vitro and in vivo." (PMID 40647481, 2025). "Then, a novel TGF-β-associated prognostic model, including SRPX2, SGCE, DES, MMP7, and KRT17, was constructed, and the risk score was demonstrated as an independent prognostic factor for gastric cancer patients." (PMID 36467074, 2022). "Among them, HEYL, MMP7, THBS1, and KRT17 are not only highly expressed in gastric cancer, but are also independent prognostic risk factors for gastric cancer." (PMID 34157940, 2021). "In summary, HEYL, MMP7, THBS1, and KRT17 are not only highly expressed in gastric cancer, but also associated with poor prognosis and may be potential prognostic biomarkers." (PMID 34157940, 2021). "Survival analysis revealed that high expression of ST2, PECAM1, CD34, and KRT17 predicted poor prognosis in patients with gastric cancer." (PMID 40860436, 2025). "Tumor cell regions were demarcated using gastric cancer-specific marker genes (KRT17/PRAME/GNGT1/GJB5/PI3)." (PMID 40452847, 2025). "Knockdown of KRT17 using targeting siRNA has been shown to significantly suppress gastric cancer cell proliferation (42.36 ± 3.2%) and migration (37.2 ± 6.2%) through the AKT/mTOR pathway." (PMID 36009022, 2022). "In gastric cancer studies, it has been shown that KRT17 is closely related to tumor size, depth of invasion, lymph node metastasis, stage of tumor lymph node metastasis, vascular invasion and poor prognosis." (PMID 34157940, 2021). "Keratin 17 expression occurred in approximately half of the gastric cancer patients in a previous study, which was positively correlated with tumor progression and poor prognosis." (PMID 32181476, 2020). "Hu and coworkers 16 demonstrated that silencing of KRT17 in gastric cancer cells inhibited cell proliferation both in vitro and in vivo conditions, reduced the migration of tumor cells and induced apoptosis by BCL2 expression." (PMID 31602265, 2019). "KRT17 is overexpressed in both psoriatic keratinocytes and tumor cells, and the topical application of KRT17 siRNA relieves psoriasiform lesions in mice and exhibits antitumor effects in gastric cancer cells." (PMID 37762693, 2023). "Similarly, in esophageal cancer, lung cancer, gastric cancer, and colorectal cancer, KRT17 knockout can inhibit cancer cell proliferation, migration, invasion, and colony formation and induce apoptosis." (PMID 35646078, 2022). "However, KRT17 is moderately expressed in thyroid cancer, lung cancer, gastric cancer, prostate cancer, ovarian cancer, head and neck cancer, and endometrial cancer." (PMID 35646078, 2022). "It was finally confirmed that HEYL, MMP7, THBS1, and KRT17 may be potential biomarkers of gastric cancer." (PMID 34157940, 2021). "After inhibiting gastric cancer cell KRT17, it inhibits proliferation and metastasis and induces apoptosis, and its mechanism of promoting tumor progression may be mainly regulated by AKT/mTOR signal." (PMID 34157940, 2021).
oral cancer (16 papers, 2016 to 2024). "Increased expression of LAMC2 has been evaluated in a variety of cancers, including esophageal, colorectal, gastric, oral squamous cell, and prostate cancers, and it has also been associated with invasiveness in cervical lesions and KRT17 in oral cancer." (PMID 32922662, 2020). "In oral cancer cells, miR-485-5p suppresses keratin 17 (KRT17), which in turn represses the integrin β4/α6/FAK/Src/ERK/β-catenin pathway, impacting cancer progression and resistance to cisplatin and carboplatin." (PMID 39771533, 2024). "In this study, we have shown for the first time that KRT17 is a potent cancer stemness modulator that contributes to therapeutic resistance in invasive oral cancer cells." (PMID 35706019, 2022). "The expression of KRT17 in oral cancer tissues was higher than that in paracancer tissues or normal tissues, while it was moderate, low or negative in paracancer tissues or normal tissues." (PMID 35281081, 2022). "In vitro and in vivo experiments, KRT17 has been shown to be highly expressed in oral cancer cell lines; KRT17 knockout can inhibit the proliferation of oral cancer cells and influence cell size." (PMID 35281081, 2022). "The high expression of KRT17 in oral cancer tissues is related to tissue differentiation, and KRT17 was highly expressed in low and medium differentiated tissues." (PMID 35281081, 2022). "In oral cancer, KRT17 stimulates the Akt/mTOR pathway and upregulates SLC2A1 and glucose uptake which facilitates tumor growth." (PMID 30214686, 2018). "Reverse transcription polymerase chain reaction (RT-PCR) showed that all the oral cancer cell lines examined expressed KRT17." (PMID 27512993, 2016). "In oral cancer, high expression of KRT17 induces EMT through the activation of the AKT pathway." (PMID 36765563, 2023). "As KRT17 was robustly induced in all the oral cancer tissues examined, the induction of AIRE in OSCC may be attributed to KRT17-mediated regulation." (PMID 32012175, 2020). "Next we examined the expression of KRT17 in oral cancer cell lines." (PMID 27512993, 2016). "Hence, studies suggest that KRT17 plays a role in the occurrence and development of oral cancer and may serve as a prognostic marker and therapeutic target." (PMID 35281081, 2022). "Some of the DEGs common to OLP and oral cancer include KRT4 (down-regulated) and KRT16, KRT17, KRT10, and KRT75 (up-regulated)." (PMID 38234400, 2023).